IL2 (interleukin 2)
Diseases named in the same sentence as IL2 in open-access papers (continued):
Sharing a sentence is not in itself a finding about the gene and the disease.
Autoimmunity (continued). "Lower classical vascular toxicity than IL-2; concerns focus on effects on differentiation balance and possible impact on autoimmunity if systemic." (PMID 41584600, 2025). "In essence, rhIL-2 lacks an appropriate therapeutic index for treatment of autoimmune conditions, and new approaches using muteins of IL-2 are being investigated." (PMID 39704171, 2024). "On the other hand, low-dose IL2 therapy has demonstrated beneficial effects in some clinical trials for the treatment of various autoimmune disorders, more specifically in patients with systemic lupus erythematosus." (PMID 38426502, 2024). "Deficits in IL-2 signaling can precipitate autoimmunity by altering the function and survival of FoxP3+ regulatory T cells (Tregs) while high concentrations of IL-2 fuel inflammatory responses." (PMID 39704171, 2024). "Given this poor availability of IL-2, it is unclear how Treg access this critical resource in vivo at sites of autoimmunity." (PMID 38378682, 2024). "IL-2 serves as the principal growth factor for antigen-activated T lymphocytes, exerting control over autoimmunity through the production of CD4+ and CD25+ to regulate T cells." (PMID 38731261, 2024). "While engineered IL-2 applications have been used in cancer and autoimmunity, our study expands this therapeutic strategy to transplantation by showing the efficacy of Treg expansion by a mIL-2 in different transplant models." (PMID 38426492, 2024). "Treatment with LD IL-2 in patients with immune-mediated diseases increases T reg numbers and controls autoimmunity." (PMID 38800484, 2024). "Disruption of the IL2R signaling pathway with a genetic defect in the gene for IL2 or IL2R complex components results in severe T-cell-related autoimmunity, suggesting a key role of ILR2 signaling in the development and function of regulatory T cells." (PMID 37626706, 2023). "A recent trend in the engineering of IL-2 for the therapy of cancer and autoimmunity is the development of PD-1-IL-2R agonists." (PMID 37516849, 2023). "Commonly, TNF activates Tregs through TNFR2 or IL2 signaling, leading to inflammatory reactions in autoimmunity, sepsis, infection and tumors." (PMID 37534250, 2023). "If the superior IL-2 capture is strongly compromised such as it is in CD25-deficient mice or in patients with risk alleles for CD25, systemic inflammation and/or autoimmunity are the consequence of the resulting Treg deficiency or disturbed Treg homoeostasis." (PMID 37741949, 2023). "UBASH3A is a negative regulator of T cell activation and IL-2 production and plays key roles in autoimmunity." (PMID 37240014, 2023). "Further, in Treg the cooperation of the trimeric receptor and the serine/threonine phosphatase PP2A confers increased sensitivity to IL-2 and PP2A deficiency in Treg results in autoimmunity." (PMID 37741949, 2023). "IL-2 directs T lymphocyte differentiation into effector and memory T cells as well as regulatory T cells which are important for preventing autoimmunity." (PMID 37560162, 2023). "The roles of IL-2 in Treg biology and suppressive function make IL-2 a highly attractive immunotherapeutic molecule in the context of autoimmunity and transplantation." (PMID 37741949, 2023). "IL-2 is critical for the sustenance of Foxp3+ Treg, and its absence leads to a significant shortage of Treg cells, resulting in autoimmunity." (PMID 38004268, 2023). "Cultured NK cells acquired exaggerated cytotoxicity against K562 tumor cells, with development of autoimmunity against healthy MSCs simultaneously in the presence of IL-2 and IL-21." (PMID 38106519, 2023). "Meanwhile, costimulation blockade continues to exert immune suppression in the presence of IL-2, as evidenced by the dramatic inhibition of tissue-specific autoimmunity seen in the presence of both reagents compared with IL-2 alone." (PMID 36347877, 2022). "Low-dose IL-2 therapy stimulates Treg proliferation and has been successfully used in models of autoimmunity and human diseases." (PMID 36429085, 2022).
Autoimmunity (continued). "Interleukin-2 (IL-2) is critical to the activation, growth, and survival of T cells and NK cells and maintains the delicate balance between autoimmunity and antineoplasm 3 surveillance." (PMID 35340585, 2022). "In contrast to the results observed in autoimmunity, an additional study from our group in human liver transplantation revealed that low-dose IL-2 increased the immunogenicity of the liver allograft, facilitating rather than preventing allograft rejection." (PMID 36389734, 2022). "Beyond animal models, low-dose recombinant IL-2 can effectively increase the number of circulating Tregs in humans and exert anti-inflammatory effects, as shown in multiple clinical trials in autoimmunity and in GVHD." (PMID 36389734, 2022). "While low doses of IL-2 were initially successfully used in the context of autoimmune conditions such as alopecia and vasculitis, further trials revealed that there is a delicate balance between tolerance and immunity even with low-dose IL-2." (PMID 36618378, 2022). "In this mini-review, the role played by IL-2 in autoimmunity, particularly its mechanistic actions on follicular helper T cells (TFH) and regulatory T cells (Treg), will be critically discussed." (PMID 35326431, 2022). "These IL-2/αIL-2 complexes, along with high-dose IL-2, are currently being studied in oncology and autoimmunity." (PMID 35819849, 2022). "Determining the cellular sources of IL-2, IL-7, and IL-15 within the thymus are important in revealing the generation of tTreg cells, and it is also important for autoimmunity treatment through the manipulation of tTreg cells." (PMID 35432378, 2022). "Treg number and function are dependent upon IL-2 signaling for proper transcriptional activity, which prevents the development of autoimmunity." (PMID 35228982, 2022). "To date, it had been proved that low-dose IL-2 (LD-IL-2) enhanced the regulatory T-cell (Treg) in autoimmune conditions." (PMID 36589282, 2022). "IL2 knockout mice exhibit lymphoproliferation and lethal autoimmunity which is prevented by adoptive transfer of normal Treg cells." (PMID 35336913, 2022). "Due to its effect on both effector and regulatory T cells, IL-2 has been evaluated as a therapeutic tool in a wide range of diseases related to cancer and autoimmunity." (PMID 36059465, 2022). "The S2A has a significantly extended half-life, and it acts as a long-acting IL-2 that primarily induces Treg activity that, in turn, suppresses autoimmunity." (PMID 33828163, 2021). "Over 40 phase 2/3 trials of low-dose IL-2 in the treatment of autoimmune conditions are currently registered, including in CD [ClinicalTrials.gov NCT01988506]." (PMID 34120187, 2021). "Previous studies showed that mice with an IL-2 knockout developed autoimmune symptoms, and that IL-2 blockage led to a rapid autoimmunity." (PMID 34692846, 2021). "IL-2 defect parallels with progression of autoimmunity and LN, and also correlates with reduced levels of Tregs." (PMID 35069220, 2021). "It is well understood that IL-2 is positioned at the interface of T cell activation and tolerance and has been developed for applications in both oncology and autoimmunity." (PMID 34804041, 2021). "ERG2 also plays an important role in controlling autoimmunity and inflammation by suppressing Th17 differentiation and in inducing anergy in murine T cells by inhibiting IL2 production." (PMID 34944796, 2021). "The concept of low-dose IL-2 therapy to treat autoimmunity was suggested because the high-affinity IL-2 receptor is known to be constitutively expressed on Tregs." (PMID 34208308, 2021). "Low dose interleukin 2 is another intriguing candidate, as interleukin 2 regulates the activity of T-cells and provides tolerance over autoimmunity in autoimmune encephalitis." (PMID 33584385, 2021). "IL-2 is a cytokine playing a role in immune memory with a proven relationship with autoimmune conditions, and the use of IL-2 or its receptors in immunotherapy is debatable." (PMID 34281739, 2021).
Autoimmunity (continued). "In fact, multiple studies have examined the use of ld-IL-2 therapy to boost Treg cell survival and function for the treatment of autoimmunity and graft-versus-host disease (GvHD)." (PMID 34324441, 2021). "Together, these studies emphasize the role of AhR activation in Treg function to abate inflammation while also suggesting a critical role of IL-2 in T cell maintenance in autoimmunity." (PMID 35008717, 2021). "Prolactin is immune stimulator and promotes autoimmunity by increasing IL-2, IFN-gamma, and autoantibody by regulating Th1 and Th2 lymphocytes, respectively." (PMID 34746311, 2021). "IL-2 is required for the maintenance and survival of CD4 Tregs50,51 and IL-2 or receptor loss leads to reduced Tregs and autoimmunity onset." (PMID 33319815, 2020). "Defective IL-2 signaling in Tregs stems from the deficiency of IL-2 or IL-2R subunits CD25 and CD122, which adversely affect Treg survival resulting in autoimmunity." (PMID 33519807, 2020). "Although high‐dose IL‐2 therapy has mostly been used to target late‐stage cancers, low‐dose infusion therapies were developed to promote Treg expansion and thereby treat autoimmunity and disorders of inflammation." (PMID 32480431, 2020). "Another study, The Interleukin-2 Therapy of Autoimmunity in Diabetes (ITAD) in T1D youth, is currently ongoing with the primary objective of evaluating the effects of ultra-low dose IL-2 administration on residual beta-cell function in new-onset patients." (PMID 32872668, 2020). "Recently, low-dose Interleukin-2 (IL-2) therapies have been tested to induce tolerance in patients with autoimmunity and inflammatory disorders." (PMID 32269069, 2020). "In this review article we discuss the IL-2 biology and current clinical application with regard to nanoparticle-based IL-2-mediated manipulation of T cell responses in autoimmunity, chronic inflammation, and cancer." (PMID 32917054, 2020). "Administration of low-dose IL2 tips the balance between Tregs and T effector cells (Teffs) towards Tregs showing great promise for the treatment of autoimmune disorders." (PMID 32111171, 2020). "To date, low doses of IL-2 have been used for expanding endogenous circulating Tregs in autoimmunity and GvHD directly in vivo." (PMID 30804926, 2019). "A common finding in trials of low dose IL-2 to treat autoimmunity is that effects are transient, declining once treatment is discontinued." (PMID 30389690, 2019). "This led to the theory that IL-2, particularly at low doses, will preferentially expand Tregs, informing preclinical experiments and clinical trials in autoimmunity." (PMID 30389690, 2019). "Although the beneficial effect of IL-2 in autoimmunity has been established some time ago, severe side effects impeded its application in the clinics." (PMID 29670626, 2018). "Our current results, however, favor a different interpretation in which, when comparable IL-2 signals are received by Treg and Tconv cells, the development of autoimmunity can be prevented." (PMID 30560927, 2018). "NOD mice exhibit a mild subclinical colitis, whereas Il2−/− mice that lack IL-2 dependent Tregs and exhibit multi-organ autoimmunity, exhibit a chronically inflamed GIT." (PMID 30662436, 2018). "In this study, we describe our efforts to engineer a pharmacologically superior and Treg-selective human IL-2 for the treatment of autoimmunity and other immune-based disorders." (PMID 30446251, 2018). "Altogether, these observations support the idea that altering Treg cell epigenetic identity, IL-2 capture and signaling leads to more rapid autoimmunity." (PMID 30560927, 2018). "Studies using knockout models for IL-2 or CD25 identified effects primarily linked to lymphoproliferation and increased autoimmunity; therefore, the dominant role of IL-2 signaling for Treg cell biology is now accepted." (PMID 29868474, 2018).
Autoimmunity (continued). "Both enhanced and disrupted IL-2 signaling have been shown to induce autoimmunity in mouse models and its alterations were found in a number of autoimmune diseases in humans." (PMID 28234966, 2017). "Both enhanced and disrupted IL-2 signaling can induce autoimmunity, indicating that there is a necessity for the maintenance of an optimal level of IL-2/IL-2R signaling given the multiple functions of this pathway." (PMID 28234966, 2017). "Tml have been shown before to represent the responsible T cell subset in the steady state that provides IL-2 for nTreg proliferation and maintenance, required to prevent autoimmunity." (PMID 28690613, 2017). "Lack of IL-2 signaling results in the death of Treg cells leading to rapid development of various autoimmune disorders, such as lymphoproliferation, colitis etc.." (PMID 28415569, 2017). "Interferon alpha also shifts the immune response to a type 1 helper (Th1)-mediated pattern, resulting in the production of potent pro-inflammatory cytokines including interferon gamma (IFN-γ) and interleukin-2 (IL-2), thereby stimulating autoimmunity." (PMID 27632981, 2016). "Anecdotally, clinicians have noted a link between autoimmunity and tumor response, such as the development of vitiligo after treatment with IL-2." (PMID 27826593, 2016). "This is obviously important for effective control of autoimmunity ensuring Treg cell activation in spatial proximity even if only rare self-reactive IL-2 secreting Th cells exist." (PMID 28035902, 2016). "IL-2 is critical for maintaining the function of the regulatory T cells (Tregs) that prevent autoimmunity." (PMID 27727279, 2016). "Aldesleukin, recombinant interleukin-2 (IL-2), was selected as a candidate immunotherapy to prevent or delay autoimmunity because previous genetic and phenotypic analyses indicate a major role for the IL-2 pathway in the development of T1D." (PMID 27727279, 2016). "The link between STAT5 and autoimmunity is often attributed to its role downstream of IL-2/IL-2Rα in Treg cells." (PMID 26999798, 2016). "Future studies will need to differentiate further the role of brain versus peripheral IL-2 and the impact of autoimmunity on CNS processes involved learning and memory." (PMID 25961067, 2015). "Deficiency in signaling through IL-2, IL-2Rα, or IL-2Rβ, or STAT5 results in lethal autoimmunity, dysregulation and decline of Treg production, and uncontrolled Teff activity leading to an imbalance between Tregs and Teff cells." (PMID 26793191, 2015). "For instance, IL-2 complexes ameliorated autoantibody-mediated autoimmunity in an experimental model for myasthenia gravis both by expanding regulatory T cells and by causing a switch from TH1 to TH2 responses." (PMID 27095999, 2015). "Increased production of IL-2 promotes immunological tolerance and ameliorates autoimmunity by stimulating T regs growth and survival, while more IL-4 and IL-5 indicates a shift towards a Th2 phenotype, which is immunosuppressive in MS and EAE." (PMID 26140285, 2015). "Regulatory T-cells induced via IL-2 and TGFβ in vitro (iTreg) suppress immune cells and are potential therapeutics during autoimmunity." (PMID 26815406, 2015). "As IL-2 is responsible for expansion and differentiation of T regulatory cells (Tregs) and also activation-induced cell death, autoimmunity arises in both IL-2−/− and CD25−/− strains." (PMID 25889094, 2015). "The Treg dependence on suitable amounts of IL-2 has been primarily demonstrated in IL-2/IL-2R knock-out mice exhibiting severe autoimmunity leading to early death." (PMID 25322151, 2014). "Recombinant AAV-mediated IL-2 expanded islet-resident Tregs, thus effectively suppressing ongoing beta cell autoimmunity at late preclinical stages and prevented the onset of long-term diabetes." (PMID 25322151, 2014).
Autoimmunity (continued). "The pivotal role of IL-2 in setting the size of the peripheral Treg compartment has led to therapeutic IL-2 administration being tested in mouse models of autoimmunity 52,98,99 and subsequently in several human clinical trials 100–103." (PMID 24712457, 2014). "The notion that Treg expansion correlated with lower IL-2 doses provided new therapeutic perspectives for tolerance induction desirable in autoimmunity." (PMID 25322151, 2014). "The cytokine IL-2 is predominantly secreted from activated T cells and is critical in regulating the balance between immune tolerance and autoimmunity." (PMID 25937895, 2014). "IL-2 appears to be the first molecule that is able specifically and directly to expand Tregs beneficial in the treatment of autoimmunity, suggesting its tremendous therapeutic potential." (PMID 25322151, 2014). "In further support of an important role for IL-2 in Treg survival, in vivo neutralization of IL-2 by the injection of an anti-IL-2 antibody results in the rapid depletion of Tregs and in the appearance of systemic, albeit limited, autoimmunity." (PMID 23801992, 2013). "Ratios of 1:1 have only transiently been achieved with IL-2/IL-2 mAb complexes where they can suppress pancreatic islet allograft rejection and autoimmunity." (PMID 23935597, 2013). "FK506 (Tacrolimus) is a potent inhibitor of calcineurin that blocks IL2 production and is widely used to prevent transplant rejection and treat autoimmunity." (PMID 23390586, 2013). "Here using these congenic IL2-KO/SCID mice, however, we were able to eliminate potential action of peripheral autoimmunity associated with IL-2 gene deletion." (PMID 24563821, 2013). "Different studies with animal models have clearly supported the involvement of IL-21 as well as IL2/IL2R pathway as potential drivers of autoimmunity." (PMID 23676143, 2013). "This notion has led to the development of promising therapeutic strategies based on low-dose IL-2 administration to boost the patients’ own Treg compartment and dampen autoimmunity and inflammation." (PMID 23801992, 2013). "To determine if reduced IL-2 responsiveness is a common feature of autoimmunity, we measured pSTAT5 in response to IL-2 in CD4+CD25hi T cells of T1D, MS and SLE patients." (PMID 24376757, 2013). "In contrast, wild-type Tregs, after adoptive transfer to IL-2−/− KO mice, fail to expand in the periphery and fail to prevent autoimmunity." (PMID 22984435, 2012). "IL-2Rβ/IL-2 knock-out mice developed a marked increase in T-cell mediated autoimmunity and deregulated T-cell proliferation." (PMID 22969748, 2012). "IL2/15Rβ-related disorders have been reported in which defective IL2/15Rβ expression leads to abnormal development of NK cells and intestinal intraepithelial lymphocytes and autoimmunity." (PMID 22662196, 2012). "In the last decade, much progress has been made in understanding the role of the IL-2/IL-2 receptor (IL-2R) axis in promoting nTreg differentiation and its importance in the interface between tolerance and autoimmunity." (PMID 21647403, 2011). "Here we first summarize the genetic and experimental evidence demonstrating a role for IL-2 in autoimmunity, mainly through the study of the NOD mouse model, and analyze the cellular and molecular mechanisms of its action on Treg cells." (PMID 21059266, 2010). "Several lines of evidence point to a critical role of the IL-2/IL-2R pathway in Treg cell development, function and homeostasis in human and murine autoimmunity." (PMID 21059266, 2010). "IL-2/anti-IL-2 complexes profoundly alter lymphocyte dynamics during homeostasis, autoimmunity and vaccination." (PMID 21170302, 2010). "In the context of COS as a regulatory element in the evolution of autoimmunity, alterations in cytokines (IL-2 expression) would exert the most significant impact next to the neoantigens." (PMID 16759382, 2006).